ATM (ATM serine/threonine kinase)
Diseases named in the same sentence as ATM in open-access papers (continued):
Sharing a sentence is not in itself a finding about the gene and the disease.
breast tumors (continued). "In ATM-associated tumours, the cumulative profile of copy number losses, gains and regions in LOH revealed several genomic regions frequently altered in breast tumours, and in particular in luminal tumours, which was consistent with the molecular subtypes defined by IHC staining in our ATM series." (PMID 29665859, 2018). "The mean expression level of TGFB1 gene was higher in sporadic compared with familial BC (2.30 ± 0.29 vs 1.55 ± 0.21; p= 0.04), whereas the mean level of ATM transcript was lower in sporadic BC compared to breast tumors with a family history (0.72 ± 0.15 vs 2.72 ± 0.56; p= 0.001)." (PMID 28881597, 2017). "Decreased ATM expression is frequently found in breast tumors, but not in premalignant lesions, and is associated with poor patients' prognosis." (PMID 23251624, 2012). "Analysis of loss of heterozygosity (LOH) in 18 breast tumors from women carrying likely pathogenic rare sequence variants revealed no consistent pattern of loss of the ATM variant." (PMID 21787400, 2011). "We compared the ATM-positive tumors with a set of age-matched control breast tumors." (PMID 21787400, 2011). "In comparison with breast tumours associated with other BC susceptibility genes, we thus confirm previous observations showing that ATM-associated tumours do not resemble BRCA1-associated tumours or PALB2-associated tumours, which are also predominantly triple-negative tumours." (PMID 29665859, 2018). "So far, no clear histopathological and molecular features of breast tumours occurring in ATM deleterious variant carriers have been described, but identification of an ATM-associated tumour signature may help in patient management." (PMID 29665859, 2018). "Altogether, ATM-associated tumours do not show the hormone receptor deficiency profile, and it is not clear whether breast tumours developed by HetAT patients could be targeted by alkylating agents or PARP inhibitors." (PMID 29665859, 2018). "In addition, knockdown of ATM expression with shRNA significantly decreased the senescent cell populations in SALL1-transfected breast tumor cells, further confirming the involvement of the ATM-associated DNA damage response in SALL1-induced tumor cell senescence." (PMID 29625565, 2018). "Blinded pathology review of 35 tumors from cases who carried a likely deleterious ATM variant and a hospital-based series of 38 age-matched control breast tumors did not reveal any distinctive pattern of histopathologic characteristics, as had been previously reported in BRCA1 tumors." (PMID 21787400, 2011). "A positive correlations among the levels of p-ATM, SOX2, and acetyl-CoA products was found in 92 clinical breast tumors." (PMID 32641713, 2020). "In the current study, we comprehensive investigated ATM, ATR and MYC expressions at the transcriptional levels (n = 1950) and at the protein level (n = 1650) breast tumours." (PMID 30746633, 2019). "Previously, we have shown that low RECQL breast tumors were significantly associated with low PARP1, BRCA1 negative, low RAD51, low ATM, low nuclear pChk1, low nuclear Chk2, low XRCC1, low FEN1, low SMUG1, and low DNA-PKcs expression." (PMID 38134458, 2023). "Our observation followed by statistical analysis of methylation status in breast tumors along with transcript expression revealed a negative correlation for TRAIL, DR4, CASP8, ATM, CHEK2, BRCA1 and BRCA2 CpG sites." (PMID 21092294, 2010).
non-small cell lung carcinoma (47 papers, 2009 to 2026). A group of at least three distinct histological types of lung cancer, including non-small cell squamous cell carcinoma, adenocarcinoma, and large cell carcinoma. "Durvalumab combined with ceralasertib showed promising clinical benefits in immunotherapy-refractory of non-small cell lung cancer, particularly in patients with Ataxia-Telangiectasia Mutated (ATM) alterations." (PMID 41601679, 2026). "Background/Objectives: This study investigated the prognostic and predictive significance of Ataxia–Telangiectasia Mutated (ATM) expression in patients with metastatic non-small-cell lung cancer (NSCLC) who were treated with pembrolizumab." (PMID 40310425, 2025). "The high frequency of germline and somatic ATM gene variants in non-small-cell lung cancer suggests their potential as prognostic biomarkers and/or predictors of therapeutic response." (PMID 40310425, 2025). "Alterations in ATM occur frequently in non-small cell lung cancer (NSCLC) and have been shown to be associated with improved local control in this cancer type." (PMID 38260227, 2024). "Analysis of tissue microarrays from 165 non-small cell lung cancer (NSCLC) patients using quantitative fluorescence immunohistochemistry identified ATM loss in 21.8% of patients." (PMID 33224881, 2020). "Abrogation of pRAD50 signalling by AZD6738 was also seen in ATM functionally deficient non-small-cell lung cancer NCI-H23 cells." (PMID 30385821, 2018). "Mutations in the Ataxia-telangiectasia mutated (ATM) gene are frequently found in human cancers, including non-small cell lung cancer (NSCLC)." (PMID 27602502, 2016). "Studies have also indicated that the ectopic expression of miR-101 is able to sensitize non-small cell lung cancer cells to radiation by targeting DNA-dependent protein kinase and ataxia telangiectasia mutated (ATM)." (PMID 25607713, 2015). "However, the use of ATM as a clinical biomarker for PARPi sensitivity is still limited, and trials in non-small cell lung cancer in which ATM is frequently mutated have proved inconclusive." (PMID 39994444, 2025). "Moreover, ATM has been implicated in enhanced epithelial-mesenchymal transition and metastatic potential in cisplatin-resistant non-small cell lung cancer (NSCLC), and downregulation of Rad51 has been shown to reduce cisplatin resistance in breast cancer cells." (PMID 34360968, 2021). "Subsequently, we extended our investigation to non-small cell lung cancer (NSCLC) patient derived xenograft (PDX) models for further validation of poly ADP-ribose polymerase inhibitor (PARPi) synthetic lethality in ATM mutant NSCLC models." (PMID 38807759, 2024). "Previous studies reported the inhibition of ATM expression by the Hsp90 inhibitor 17-DMAG in non-small cell lung cancer cell lines." (PMID 34072430, 2021). "Cisplatin was previously reported to induce the MICA and MICB expression in non-small-cell lung cancer A549 cell line, through DNA stress-induced ATM-ATR signalling, resulting in enhanced sensitivity to NK cell-mediated cytotoxicity." (PMID 29805983, 2018). "The results of this study are consistent with previous findings in non-small cell lung cancer where kotomolide decreased proliferation via the activation of ATM." (PMID 28881600, 2017).
non-small cell lung carcinoma (continued). "When DNA double-strand breaks, ATM is a DNA damage signaling, and the reduction of ATM was found in CRC tumors, Plk1 was elevated in carcinomas of the non-small cell lung and other types of tumor, and it’s also play a crutial role in G2/M checkpoint recovery." (PMID 33925358, 2021). "We found that Gαs inhibits ATM activation via the Gαs-cAMP-PKA-PP2A pathway and augments radiation-induced apoptosis following γ-ray irradiation in non-small cell lung cancer cells." (PMID 24568192, 2014). "The anticancer mechanisms of AITC in human A549 and H1299 non-small cell lung cancer (NSCLC) cells were reported to be due to S and G2/M cell cycle arrest, γH2AX, FANCD2 foci, and ATM/ATR-mediated checkpoint responses that induced replication stress in NSCLS cells." (PMID 36135016, 2022).
cervical carcinoma (42 papers, 2012 to 2026). A carcinoma arising from either the exocervical squamous epithelium or the endocervical glandular epithelium. "Altogether, we present evidence that synthetic lethality using ATM/CHK2 inhibitors can be exploited to treat cervical cancer and other HPV-associated tumors." (PMID 35745491, 2022). "One study also examined the predictive and prognostic role of phosphorylated (p-)ATM expression in cervical cancer and it was found that high levels of p-ATM was associated with poor loco-regional tumor control (HR = 1.817, p = 0.006)." (PMID 33224881, 2020). "The aim of this study was to evaluate the role of the ATM D1853N (5557G>A) and p53bp1 D353E (1236C>G) polymorphisms in the development of cervical cancer in Portugal." (PMID 22200742, 2012). "This study aimed to evaluate the role of the ATM D1853N (5557G>A) and 53bp1 D353E (1236C>G) polymorphisms in the development of cervical cancer, using TaqMan® SNP Genotyping Assays." (PMID 22200742, 2012). "This is the first study to evaluate the role of the ATM D1853N (5557G>A) and p53bp1 D353E (1236C>G) polymorphisms in the development of cervical cancer in Portugal." (PMID 22200742, 2012). "Genes with known or likely deleterious variants among cervical cancer patients with DDR gene alterations were ATM (n = 3, 2.33%), BRCA2 (n = 3, 2.33%), ATR (n = 2, 1.55%), CHEK2 (n = 2, 1.55%), followed by BRCA1 (n = 1, 0.78%), FANCA (n = 1, 0.78%), MSH6 (n = 1, 0.78%), and RAD51D (n = 1, 0.78%)." (PMID 35071000, 2021). "Similarly, analysis of phosphorylated ATM (p-ATM) expression in cervical cancer patients revealed an association between high nuclear p-ATM expression in tumor samples and locoregional disease free survival, as well as poor response to chemotherapy." (PMID 26275218, 2015). "Therefore, increased expression of the ATM gene is believed to play a role in radiation resistance in advanced cervical cancer.Sad to say, the underlying mechanism remains unclear." (PMID 38651153, 2024). "Inhibition of ATM activity or depletion of ATM sensitised cervical cancer lines to Olaparib, in line with numerous previous studies demonstrating that ATM deficiency correlates with PARPi sensitivity." (PMID 39994444, 2025). "Among them, The expression of ATM was higher in the cervical cancer group than the CIN group (P < 0.05)." (PMID 35379200, 2022). "We retrieved related literature and found that lncRNAs can regulate the expression of ATM in various tumors, including cervical cancer, esophageal squamous cell cancer, pancreatic cancer, and thyroid cancer." (PMID 36685972, 2022). "To verify the cervical cancer cell lines dependency on ATM/CHK2 signaling pathway upon DNA damage we treated HeLa and SiHa cells with doxorubicin and/or cisplatin." (PMID 35745491, 2022). "A literature search revealed that ATM is highly expressed in cervical cancer, and ATM expression inhibition can enhance the sensitivity of cervical cancer to radiotherapy and chemotherapy." (PMID 35379200, 2022). "Altogether, these data indicate that HPV-positive cervical carcinoma cell lines are strongly dependent on ATM/CHK2 pathway for their survival." (PMID 35745491, 2022). "Concordantly, clonogenic survival analysis revealed inhibition of ATM to lead to pronounced radio-sensitivity of cervical cancer cells." (PMID 33224881, 2020). "Osthole treatment also sensitized cervical cancer to irradiation, revealing promoted DNA damage and prohibited ATM/NF-κB signaling." (PMID 32655987, 2020).
cervical carcinoma (continued). "Similar findings were observed in experiments using shRNA mediated ATM knockdown in human cervical cancer epithelial (Hela) cells." (PMID 24957606, 2014). "Our study shows a critical role for active ATM in the response of cervical cancer to irradiation, both in cervical cancer cell lines as well as in patients with cervical cancer treated with (chemo)radiation." (PMID 22323184, 2012). "In summary, on the basis of our results, high phospho-ATM levels is an independent predictor for poor response in cervical cancer." (PMID 22323184, 2012). "Altogether, our results indicate a differential requirement for ATM or 53BP1 with respect to irradiation-induced cell cycle arrest and show that ATM inhibition dramatically radiosensitises cervical cancer cells as judged by survival assays." (PMID 22323184, 2012). "HPV-positive cervical cancer cells require both ATM activity and the presence of 53BP1 for induction of this irradiation-induced G1 arrest." (PMID 22323184, 2012). "In conclusion, both our in vitro and patient-related findings indicate a protective role for ATM in response to (chemo)radiation in cervical cancer and point at ATM inhibition as a possible means to improve the efficacy of (chemo)radiation." (PMID 22323184, 2012). "We investigated the role of ATM and 53BP1 in the cellular response to irradiation in cervical cancer cells." (PMID 22323184, 2012). "To investigate the predictive value of ATM activity for response to irradiation in cervical cancer cells, we analysed the levels of phospho-Ser1981-ATM before and after irradiation." (PMID 22323184, 2012). "This is the first study to evaluate the role of ATM G5557A and P53BP1 C1236G polymorphisms in cervical cancer susceptibility." (PMID 22200742, 2012). "ATM has been proved to be connected with therapeutic effects of radiotherapy in cervical cancer." (PMID 36685972, 2022). "Therefore, in order to confirm if ATM is critical for maintaining cervical cancer-derived cell lines proliferation, we treated HeLa and SiHa cell lines, as well as normal PHK, with 2 mM caffeine and 10 μM KU-55933." (PMID 35745491, 2022). "Considering this, we aimed to investigate if the expression of these oncoproteins could play a role in the sensitivity of cervical cancer-derived cell lines to ATM and CHK2 inhibition." (PMID 35745491, 2022). "Moreover, we show that gene silencing or chemical inhibition of the kinases encoded by ATM and CHEK2 reduced the clonogenic and proliferative capacity of cervical cancer-derived cells." (PMID 35745491, 2022). "Based on preclinical evidence, the response to chemo/radiation therapy may be increased using ATM or Chk1 inhibitors for cervical cancer patients." (PMID 34620846, 2021). "Roossink at al tested whether tumoral ATM expression was predictive for treatment outcome with adjuvant chemo-radiothrerapy in 375 patients with advanced cervical cancer." (PMID 33224881, 2020).